CYP26B1 (cytochrome P450 family 26 subfamily B member 1)
Diseases named in the same sentence as CYP26B1 in open-access papers (continued):
Sharing a sentence is not in itself a finding about the gene and the disease.
tumor (17 papers, 2014 to 2025). "We detected that TNFRSF12A, IL1R1, ELN and CYP26B1 were unfavorable prognostic factors that were overexpressed in tumor tissues and associated with poor survival in the TCGA-BLCA cohort." (PMID 38216619, 2024). "CYP26B1 negative/weak/moderate expressing tumours when compared with CYP26B1 strongly expressing tumours also showed a highly significant association with survival (HR = 1.737, 95%CI = 1.248–2.418, χ2 = 11.092, p = 0.001)." (PMID 24608339, 2014). "In vitro experiments confirmed that overexpression of CYP26B1 can significantly enhance the proliferation and migration of tumor cells." (PMID 40535799, 2025). "Tumor tissues exhibited high expression levels of CYP26B1, MCM10, SPINK4, and TRIM54 in the current study." (PMID 38870259, 2024). "Tumor tissues exhibited elevated expression levels of CYP26B1, MCM10, SPINK4, and TRIM54 compared to normal liver tissues, as indicated by the results." (PMID 38870259, 2024). "This analysis identified TRIM36, CYP26B1, PAGE1, CDK5R2, and DCAF8L1 as a molecular signature associated with tumor aggressiveness." (PMID 38649860, 2024). "The Cu-PS, a 5-genes (C7, MAGEA6, HK2, CYP26B1 and EPO) signature, was significantly associated with TNM stage, tumor mutational burden (TMB), drugs sensitivity, and immunotherapies response." (PMID 36250008, 2022). "In MMR proficient tumours there was a consistent relationship between the intensity of CYP26B1 expression and overall survival." (PMID 24608339, 2014). "CYP26B1 and LRAT both showed significant associations with tumour site, tumour (T) stage, extramural venous invasion and overall stage." (PMID 24608339, 2014). "In this study we found prognostic significance for CYP26B1 in both the whole patient cohort and in those tumours which were defined as microsatellite intact or stable." (PMID 24608339, 2014). "In mismatch repair proficient tumours strong CYP26B1 (HR = 1.330, 95%CI = 1.173–1.509, χ2 = 21.493, p<0.001) and strong LRAT (HR = 1.464, 95%CI = 1.110–1.930, χ2 = 7.425, p = 0.006) were also associated with poorer prognosis." (PMID 24608339, 2014). "The mean survival for the CYP26B1 negative/weak/moderate group (n = 564) was 119 months (95%CI = 111–128 months) whereas the mean survival for CYP26B1 strong tumours (n = 58) was 80 months (95%CI = 60–101 months)." (PMID 24608339, 2014). "CYP26B1 was moderately or strongly expressed in 25.2% of tumours and was significantly less expressed in normal colonic epithelium (p<0.001)." (PMID 24608339, 2014). "Single-cell analysis further revealed that CYP26B1 expression was negatively correlated with DNA damage repair, suggesting that CYP26B1 may contribute to tumor progression by impairing the DNA damage response." (PMID 40535799, 2025). "It was found that CYP26B1 is significantly correlated with tumor stemness and differentiation." (PMID 40535799, 2025). "Furthermore, we found that there is a significant positive correlation between CYP26B1 and an increase in tumor-infiltrating lymphocytes." (PMID 40535799, 2025). "Additionally, we analyzed and verified the relationship between CYP26B1 and tumor immune microenvironment by multiplex immunohistochemical (mIHC)." (PMID 40535799, 2025). "Comparing CYP26B1 negative and weakly positive tumours with CYP26B1 moderate and strong expressing tumours showed that there was a highly significant association with survival (HR = 1.465, 95%CI = 1.151–1.865, χ2 = 9.832, p = 0.002)." (PMID 24608339, 2014). "Comparing CYP26B1 negative and weakly positive tumours with CYP26B1 moderate and strong expressing tumours showed a highly significant association with survival (HR = 1.617, 95%CI = 1.242–2.105, χ2 = 12.962, p<0.001)." (PMID 24608339, 2014).
tumor (continued). "CYP26B1 negative/weak/moderate expressing tumours when compared with CYP26B1 strongly expressing tumours also showed a highly significant association with survival (HR = 1.948, 95%CI = 1.366–2.777, χ2 = 14.149, p<0.001)." (PMID 24608339, 2014). "CYP26B1 was independently prognostic in a multivariate model both in the whole patient cohort (HR = 1.177, 95%CI = 1.020–1.216, p = 0.026) and in mismatch repair proficient tumours (HR = 1.255, 95%CI = 1.073–1.467, p = 0.004)." (PMID 24608339, 2014). "Recognizing the critical role of m1A in tumor progression and prognosis, a reliable prognostic signature based on five DEGs characterizing autophagy among the m1A modification patterns (CDK5R2, CYP26B1, DCAF8L1, PAGE1, and TRIM36) was initially established." (PMID 38649860, 2024). "Immunohistochemistry analysis showed that CYP26B1, MCM10, SPINK4, and TRIM54 were highly expressed in tumor tissue compared to normal tissue." (PMID 38870259, 2024). "In contrast, Moonlight identified SOX7, CYP26B1, DACT2 as tumor suppressors with low expression in these same cell lines." (PMID 31900418, 2020). "For CYP26B1 negative tumours (n = 200) the mean survival was 143 months (95%CI = 127–158 months) while for CYP26B1 positive tumours (n = 322) the mean survival was 104 months (95%CI = 94–114 months)." (PMID 24608339, 2014). "Comparing CYP26B1 negative tumours with tumours that showed any CYP26B1 immunoreactivity then poorer survival was associated with CYP26B1 expression (HR = 1.352, 95%CI = 1.054–1.735, χ2 = 5.707, p = 0.017)." (PMID 24608339, 2014). "The mean survival for the CYP26B1 negative/weak/moderate group (n = 473) was 123 months (95%CI = 113–132 months) and the mean survival for CYP26B1 strongly expressing tumours was 77 months (95%CI = 56–98 months)." (PMID 24608339, 2014). "Comparing CYP26B1 negative tumours with tumours that showed any CYP26B1 immunoreactivity then poorer survival was associated with CYP26B1 expression (HR = 1.604, 95%CI = 1.207–2.132, χ2 = 10.796, p = 0.001)." (PMID 24608339, 2014). "For CYP26B1 negative tumours (n = 242) the mean survival was 133 months (95%CI = 118–148 months) while for CYP26B1 positive tumours (n = 380) the mean survival was 107 months (95%CI = 98–116 months)." (PMID 24608339, 2014). "Compared with their adjacent noncancerous tissues, tumor tissues exhibited the consistent downregulation mRNA of CYP26A1 and CYP26B1 in patients number 2, 3, 5, and 6 (expression >2-fold change in numbers 2, 3, and 5)." (PMID 25839051, 2015).
cancer (15 papers, 2013 to 2026). A tumor composed of atypical neoplastic, often pleomorphic cells that invade other tissues. "Arecoline can stimulate the high expression of CYP26B1 or cellular at-RA, causing cancer cells to carry on the apoptosis pathway and to maintain balance and survival, resulting in CYP26B1 overexpression." (PMID 25114974, 2014). "The results indicated that patients with late-stage (stage III or stage IV) carcinoma exhibited a greater than 2-fold change in expression of the CYP26B1 splice variant." (PMID 25114974, 2014). "CYP26B1 has been linked to various cancers due to its ability to modulate RA levels." (PMID 40535799, 2025). "Several studies have already discovered differential gene expression in cancer cell-lines based on global gene expression analysis, such as CYP26B1, DHRS3, and TINAGL1 were up-regulated by ATRA." (PMID 39210795, 2025). "CYP26A1 expression was lower in the cancer tissue of number 7 compared with its adjacent tissue, but the expression of CYP26B1 was higher in the cancer tissue than in the adjacent tissue." (PMID 25839051, 2015). "We observed that arecoline can induce expression of both forms of CYP26B1 and that this induction rate is greater for full-length CYP26B1 in cancer cells (i.e., Ca9-22)." (PMID 25114974, 2014). "CYP26B1's function in degrading RA suggests that its dysregulation could lead to altered RA signaling, influencing both cancer cell behavior and the immune microenvironment." (PMID 40535799, 2025). "Correspondingly, the marker genes, except PIK3R3 and CYP26B1, revealed elevated transcriptional enrichment scores in at least eight different cancer entities compared to healthy tissue shown by pan‐cancer expression analysis using the TNMplot web tool, emphasizing their general role in cancer." (PMID 39825568, 2025). "Expression of the CYP26B1 splice variant was 2-fold higher in 6 of 8 cancer tissues (75%) than in adjacent noncancerous tissues." (PMID 25114974, 2014). "Most HCC tissues exhibited elevated protein levels of CDK5R2, CYP26B1, DCAF8L1, PAGE1, and TRIM36 in comparison to para-carcinoma tissues, as indicated by the results." (PMID 38649860, 2024). "In the cancer tissue of number 4, a slightly decreased expression of CYP26A1 and increased expression of CYP26B1 were found." (PMID 25839051, 2015). "The risk of developing oral malignant disorders may be related to the functionally relevant combined effects of SNPs such as those in CYP26A1, CYP26B1, and CYP26C1 within and between different cancer pathways." (PMID 31465460, 2019). "Through the SAM calculation process, ACTA1, ASPN, C4orf7, CYP26B1, and PRAME showed statistically significant differences in expressions between early and late stages of cancer in both Asian and non-Asian samples." (PMID 24982892, 2014).
infection (3 papers, 2016 to 2025). The state of being infected such as from the introduction of a foreign agent such as serum, vaccine, antigenic substance or organism. "Several genes involved in RA metabolic processes, which are known to be inducible by RA, were significantly downregulated in the colon of the VAS mice during peak infection, including Aldh1a1, Aldh1a2, Cyp26b1, and Lrat." (PMID 35458125, 2022). "Notably, genes such as Cyp26b1, Dbp, Kcng1, Cdca7l, Paxip1, Stxbp2 and Gpi1 were also observed to be significantly up-regulated (p<0.05) in the hMHC mice on various days post-infection." (PMID 40822594, 2025).
skeletal dysplasia (1 paper, 2018). Any Mendelian diseases that affects growth and development of the skeleton. "Recently, an autosomal recessive disorder of skeletal dysplasia associated with CYP26B1 was reported in three families, in which the patients were all homozygous variations." (PMID 29606097, 2018). "NAGLU and CYP26B1 mutations were related to MPS IIIB and skeletal dysplasia, respectively." (PMID 29606097, 2018).
CYP26B1 also shares sentences with these, for which no sentence is quoted: breast carcinoma (2 papers); depression (2); melanoma (2); Antley-Bixler syndrome (1); asthenozoospermia (1); asthma (1); autism spectrum disorder (1); Azoospermia (1); cannabis dependence (1); ciliopathies (1); cleft palate (1); craniostenosis (1); diabetic cardiomyopathy (1); early onset epileptic encephalopathy (1); Encephalocele (1); epilepsy (1); gastrointestinal disorders (1); Granuloma (1); Hand Osteoarthritis (1); inflammation (1); Intellectual disability (1); knee osteoarthritis (1); liver cancer (1); lung carcinoma (1); lymph node metastasis (1); memory impairment (1); microcephaly (1); occipital encephalocele (1); osteoarthritis (1); Osteochondroma (1).
A further 8 diseases each share a sentence with CYP26B1 in 1 paper.